FGF23 (fibroblast growth factor 23)
Diseases named in the same sentence as FGF23 in open-access papers (continued):
Sharing a sentence is not in itself a finding about the gene and the disease.
ciliopathies (1 paper, 2022). "Utilizing the ta2 avian mutant as a model for a human ciliopathy, we identified disruptions in the FGF23–PTH signaling axis concomitant with decreased bone mineralization and increased serum calcium." (PMID 35818799, 2022). "As Hh and Wnt signaling have numerous roles throughout the embryo at this stage of skeletogenesis, focusing specifically on FGF23 signaling may prove to be the most targeted mode of treatment for pleiotropic diseases, like ciliopathies, with skeletal phenotypes." (PMID 35818799, 2022). "These similarities served as the premise for testing the hypothesis that the FGF23–PTH axis was not only disrupted in skeletal ciliopathies, but also served as a potential therapeutic avenue for the treatment of ciliopathies." (PMID 35818799, 2022).
coinfection (1 paper, 2016). The simultaneous infection of a host by multiple pathogen species. "Similarly, our data suggest that HCV infection in HIV-negative persons is insufficient to affect FG23 levels, while HCV co-infection among HIV-positive individuals is associated with increased FGF23 levels." (PMID 27176000, 2016). "Among HIV-positive subjects, factors associated with higher FGF23 levels at baseline included being female (adjusted ratio of geometric means; 95% confidence interval [CI]), 1.46;1.21, 1.76), serum phosphorus (1.21 per mg/dL higher; 1.03, 1.42), and HCV coinfection (1.31;1.10, 1.56)." (PMID 27176000, 2016). "We found significant independent associations of FGF23 level with both non-suppressed HIV RNA and with HCV coinfection." (PMID 27176000, 2016).
cyst (1 paper, 2020). A sac-like closed membranous structure that may be empty or contain fluid or amorphous material. "In rodent models, resistance to high FGF23 levels produced in the cyst-lining cells was also reported." (PMID 32178226, 2020).
deep vein thrombosis (1 paper, 2021). "A 59-year-old male with a history of factor V Leiden mutation, pulmonary embolism, and deep vein thrombosis was diagnosed with oncogenic osteomalacia in 2008 following laboratory findings significant for low phosphorus and elevated FGF-23 levels." (PMID 34268038, 2021).
dysplasia (1 paper, 2019). A usually neoplastic transformation of the cell, associated with altered architectural tissue patterns. "Clinical cases have found that elevated levels of fibroblast growth factor 23 in patients with dysplasia are associated with HRAS mutations." (PMID 31781279, 2019).
ear malformation (1 paper, 2016). "FGF23-deficient mice show a mixed hearing loss and middle ear malformations, and changes in circulating FGF23 have been observed in humans and mice with ENPP1 and PHEX deficiencies." (PMID 27959908, 2016).
embryonal carcinoma (1 paper, 2025). A non-seminomatous malignant germ cell tumor characterized by the presence of large germ cells with abundant cytoplasm resembling epithelial cells, geographic necrosis, high mitotic activity, and pseudoglandular and pseudopapillary structures formation. "Here, we show that fibroblast growth factor 23 (FGF23), a regulator of phosphate homeostasis, is expressed in testicular germ cell neoplasia in situ (GCNIS), embryonal carcinoma (EC), and human embryonic stem cells." (PMID 40279260, 2025).
endocarditis (1 paper, 2015). Inflammation of the endocardium. "Moreover, patients with endocarditis and patients requiring resternotomy had significantly higher FGF23 serum concentrations (data not shown)." (PMID 25902817, 2015).
endometriosis (1 paper, 2025). The growth of functional endometrial tissue in anatomic sites outside the uterine body. "The immunohistochemical analysis focused on the expression of IFN-τ, FGF-7, FGF-10, FGF-23, and HGF in both normal endometrial tissues and deep endometriosis samples." (PMID 40076699, 2025). "In contrast, FGF-23 and IFN-τ showed significantly higher expression in the ectopic endometrial stroma of endometriosis samples relative to eutopic endometrium, whereas no notable differences in epithelial expression were observed between the two tissue types." (PMID 40076699, 2025).
falciparum malaria (1 paper, 2018). "Conventional iron markers and FGF23 were measured in children with acute falciparum malaria and after 1, 2, 4, and 6 weeks." (PMID 30537973, 2018). "In this observational, longitudinal study, conventional iron markers as well as FGF23 were measured in children on admission with acute falciparum malaria and after 1, 2, 4 and 6 weeks." (PMID 30537973, 2018).
giant cell tumour (1 paper, 2024). "FGF23 expression was reported in giant cell tumour tissue; however, the authors did not specify whether the protein was expressed in spindle cells or osteoclast-like giant cells." (PMID 38397231, 2024).
glioma (1 paper, 2016). A benign or malignant brain and spinal cord tumor that arises from glial cells (astrocytes, oligodendrocytes, ependymal cells). "In the RMPAlow gliomas, a different set of RTK signaling-related genes including MET (8.9%), EPHA1 (8.9%), EPHB6 (8.9%), EPHB4 (8.3%), BRAF (8.9%), FGF6 (11.9%), FGF23 (11.9%), NTF3 (11.9%), and ANGPT1 (9.5%) were amplified." (PMID 27385209, 2016).
Glucose intolerance (1 paper, 2020). Glucose intolerance (GI) can be defined as dysglycemia that comprises both prediabetes and diabetes. "Median of leptin and FGF21, but not of FGF23, were statistically higher in patients with DMT2 and fasting glucose intolerance." (PMID 32570721, 2020).
growth deficiency (1 paper, 2016). "Novel therapy with FGF23 neutralizing antibodies has shown that inhibition of excess FGF23 activity correct growth deficiency in mice, and anti-FGF23 antibodies are currently being tested in human XLHR." (PMID 26543054, 2016).
head and neck cancer (1 paper, 2025). A primary or metastatic malignant neoplasm affecting the head and neck. "In head and neck cancer, the mutation frequency of FGF genes was relatively uniform, ranging from 7% to 14%, with FGF23 showing a distinct mutation profile." (PMID 40001587, 2025). "In contrast, the relatively consistent mutation frequencies in head and neck cancer suggest that FGF genes, with the exception of FGF23, may play more conservative roles in tumor progression." (PMID 40001587, 2025).
Headache (1 paper, 2023). Cephalgia, or pain sensed in various parts of the head, not confined to the area of distribution of any nerve. "Another recent GWAS including 2084 Taiwanese patients and 11,822 age- and sex-matched controls identified two loci, rs10493859 in TGFBR3 and rs13312779 in FGF23, both functionally relevant to vascular function and migraine, to be significantly associated with self-reported headache." (PMID 36800925, 2023).
hemangioma (1 paper, 2016). A benign vascular lesion characterized by the formation of capillary-sized or cavernous vascular channels. "On the basis of these two converging lines of evidence suggesting a role for HIF-1α in FGF23 production and in hemangioma tumor progression, we explored the hypothesis that aberrant FGF23 production in TIO tumors might also occur though a HIF-1α-dependent mechanism." (PMID 27468359, 2016).
hemorrhage (1 paper, 2024). Loss of blood from the vascular compartment to the exterior or into nonvascular body space as a result of rupture or severance of the blood vessels. "The connections between FGF-23 and rhEpo are very complex and varied, and the role of Epo as a regulator of FGF-23 production was first investigated in a mouse model of acute hemorrhage." (PMID 39684548, 2024).
Hepatitis (1 paper, 2024). Inflammation of the liver. "Immunohistochemical and RNA-FISH analyses of hepatitis tissue revealed that FGF23 mRNA was expressed in both hepatocytes and Kupffer cells." (PMID 39525686, 2024).
hereditary anemia (1 paper, 2019). "Besides activity of the pathway, the contribution of other factors influencing FGF23 signaling in hereditary anemias, including inflammation and iron load, remains to be investigated." (PMID 30971944, 2019). "Moreover, the role of the individual FGFRs and α-KL in FGF23 signaling in hereditary anemia is currently unknown." (PMID 30971944, 2019).
hip fracture (1 paper, 2024). Traumatic or pathological injury to the hip in which the continuity of either the femoral head, femoral neck, intertrochanteric or subtrochanteric regions is broken. "Our data suggest that either FGF-23 or IL-15RA or both should be assessed as potential biomarkers to make accurate clinical decisions regarding risk of postoperative AKI and to evaluate the risk of mortality and complications in frail hip fracture patients." (PMID 38919625, 2024). "However, none of the studies had investigated the role of FGF-23 as a biomarker of AKI in hip fracture patients, even though post-operative incidence of AKI is known to risk factor of hip fracture mortality." (PMID 38919625, 2024).
hippocampal atrophy (1 paper, 2025). "Experimental studies have shown that FGF-23 can induce hippocampal atrophy and directly damage the cognitive function of CKD patients through its toxic effect on hippocampal neurons and synapses." (PMID 40950978, 2025).
hookworm infections (1 paper, 2022). "We also did not collect information that may have influenced vitamin D or iron status such as dietary intake, sunlight exposure or hookworm infections and did not measure 1,25(OH)2D, FGF23, vitamin D binding protein, parathyroid hormone, or calcium concentrations." (PMID 35405984, 2022).
hypervitaminosis A (1 paper, 2013). A symptom complex resulting from ingesting excessive amounts of vitamin A. "Neither serum Fgf23 levels nor serum phosphate levels were significantly different in the rats suffering from hypervitaminosis A compared to controls." (PMID 24340023, 2013).
idiopathic scoliosis (1 paper, 2023). A scoliosis with no known cause. "Currently, there are limited reports in the literature on Klotho protein and FGF-23 levels in adolescent idiopathic scoliosis." (PMID 37686090, 2023).
lactic acidosis (1 paper, 2022). Metabolic acidosis characterized by the accumulation of lactate in the body. "As higher FGF23 levels are associated with poorer outcome in several disorders including kidney and cardiovascular diseases, higher FGF23 in severe lactic acidosis may also be indicative of a dismal prognosis." (PMID 34731356, 2022). "Taken together, our study demonstrates that lactic acid induces Fgf23 gene expression and protein synthesis in vitro at concentrations encountered in vivo in lactic acidosis." (PMID 34731356, 2022). "High FGF23 concentrations in lactic acidosis may be suggestive for poor prognosis, although clinical studies are needed for clarification." (PMID 34731356, 2022). "This supports the notion that lactic acid may be a relevant stimulator of FGF23 production also in vivo, at least in pathological lactic acidosis." (PMID 34731356, 2022). "Lactic acidosis may, therefore, be paralleled by a surge in plasma FGF23." (PMID 34731356, 2022).
leukemia (1 paper, 2021). A malignant (clonal) hematologic disorder, involving hematopoietic stem cells and characterized by the presence of primitive or atypical myeloid or lymphoid cells in the bone marrow and the blood. "Further, response elements in Fgf23 promoter fragments were activated in response to 1,25D in human K562 leukemia cells." (PMID 34799645, 2021).
liver abscesses (1 paper, 2025). "Considering that F. necrophorum is the primary etiological agent reported in liver abscesses in cattle, the up-regulation of FGF23 in our study suggests that LPS from the bacteria could trigger higher FGF23 production." (PMID 40489480, 2025).
liver failure (1 paper, 2018). A liver disease characterized by the liver losing or has lost all of its function. "FGF23 expression has been speculated to be unrelated to serum and urinary P. Moreover, FGF23 produced in the kidneys in a PKD model and subjects with liver failure originates from the increased FGF23 concentration in the blood." (PMID 29518087, 2018).
lupus nephritis (1 paper, 2023). Glomerulonephritis in the context of systemic lupus erythematosus. "In this sense, a previous study showed higher levels of FGF23 in 15 premenopausal patients with newly diagnosed lupus nephritis (≤2 months) compared to 15 age-matched healthy controls." (PMID 37627287, 2023).
Lyme disease (1 paper, 2023). Lyme disease (named after the towns in the USA where the disease was first identified) is a bacterial infection caused by Borrelia burgdorferi. "FGF23 upregulation, in addition, was observed in response to the Lyme disease bacterium." (PMID 36650549, 2023).
Mazabraud syndrome (1 paper, 2025). Mazabraud syndrome is a rare primary bone dysplasia characterized by the association of fibrous dysplasia with intramuscular myxomas. "Additionally, phosphate-wasting due to fibroblast growth factor 23 (FGF-23) overexpression and the presence of intramuscular myxomas characterize Mazabraud’s syndrome." (PMID 40831852, 2025).
morbid obesity (1 paper, 2013). An excess of body weight, normally defined as an individual with a body mass index greater than 35 or a body weight greater than one hundred percent of ideal body weight. "We here characterize that this association depends on the FGF-23 assay and on the presence of morbid obesity." (PMID 23555610, 2013).
muscle disorders (1 paper, 2025). "Although XLH is characterized by muscle disorders, to date there are few studies on the action of FGF23 on muscle." (PMID 40926139, 2025). "All these collected data suggest that FGF23 is indeed involved in the muscle disorders that occur in XLH." (PMID 40926139, 2025).
osteochondrodysplasia (1 paper, 2025). A term referring to disorders characterized by abnormalities in the development of bones and cartilage. "Thus, there appears to be a dissociation between osteochondrodysplasia (driven by any variant leading to FGFR1 activation) and FGF23 excess (driven by only specific activating variants) in OGD." (PMID 41473314, 2025).
Osteochondrosis (1 paper, 2025). Abnormal growth ossification centers in children. "It is well known that the main cause of osteochondrosis in PMT is the massive secretion of a phosphoregulatory factor FGF23 by the tumor tissue." (PMID 40890774, 2025).
osteonecrosis (1 paper, 2024). A none disease characterized by death of bone tissue due to a lack of blood supply. "FGF23 silencing attenuated steroid-induced osteonecrosis of the femoral head by inhibiting the pyroptosis signaling pathway, and promoting osteogenic differentiation of BMSCs and angiogenesis of HUVECs in vitro." (PMID 39009650, 2024).
overnutrition (1 paper, 2023). An imbalanced nutritional status resulting from excessive intake of nutrients. "Therefore, we evaluated the effect of FGF-23 under conditions mimicking the pathophysiologic situation of overnutrition." (PMID 36437429, 2023).
pancreatitis (1 paper, 2023). Inflammation of the pancreas. "As increased DGGR lipase activity in dogs is indicative for pancreatitis, further studies for the relationship between CKD-induced FGF-23 elevation and inflammatory diseases such as pancreatitis in dogs are needed." (PMID 37893926, 2023).
pericardial effusion (1 paper, 2013). Fluid collection within the pericardial sac, usually due to inflammation. "Neither pericardial effusion, nor the overall signs of cardiac involvement (in the whole) were significantly associated with the FGF23 polymorphism." (PMID 24168888, 2013).
polyarthritis (1 paper, 2022). "Paraneoplastic rheumatologic conditions such paraneoplastic polyarthritis and hypertrophic osteoarthropathy are a few notable examples and are thought be related to upregulation of VEGF and fibroblast growth factor 23 (FGF23) in tumors." (PMID 36672607, 2022).
postmenopausal osteoporosis (1 paper, 2025). Metabolic disorder associated with fractures of the femoral neck, vertebrae, and distal forearm. "Elevated FGF23 has been linked to postmenopausal osteoporosis, with several studies showing a negative correlation between serum FGF23 levels and BMD in postmenopausal women." (PMID 41367909, 2025).
progeria (1 paper, 2021). "The pathophysiology of CKD-MBD is becoming clear with the emerging of αKlotho, originally identified as a progeria-causing protein, and bone-derived phosphaturic fibroblast growth factor 23 (FGF23) as associated factors." (PMID 34069053, 2021).
renal carcinoma (1 paper, 2015). A carcinoma arising from the epithelium of the renal parenchyma or the renal pelvis. "The short, alternative t5 form of heparanase expressed by renal cancers was not increased by FGF23." (PMID 25944690, 2015). "The t5 alternate form of heparanase found in renal cancers was not increased by FGF23." (PMID 25944690, 2015).
scleroderma (1 paper, 2017). Scleroderma is a rare autoimmune connective tissue disorder characterized by abnormal hardening of the skin and, sometimes, other organs. "Some weaknesses of our study were no measurement of bone density and the possible effects of consumed drugs in the scleroderma patients on Klotho, vitamin D, iPTH, as well as FGF-23 levels." (PMID 28540270, 2017). "In the present study, we evaluated some of the main factors involved in calcium and phosphate homeostasis including serum FGF-23, Klotho, vitamin D, and iPTH levels in the scleroderma patients compared with the healthy individuals." (PMID 28540270, 2017). "The purpose of this study was to evaluate serum Klotho, FGF-23, intact PTH (iPTH) and vitamin D levels in scleroderma patients compared with the healthy controls." (PMID 28540270, 2017). "According to the important roles of vitamin D, FGF-23, as well as Klotho in calcium metabolism, the aim of the present study was to evaluate serum Klotho, FGF-23, and 25-hydroxy Vit D levels in the scleroderma patients compared with the healthy controls." (PMID 28540270, 2017).
secondary hypertension (1 paper, 2015). High blood pressure caused by an underlying medical condition. "The increase in FGF23 in those patients led to an early development of secondary hypertension by suppression of 1,25(OH)2D production, and low phosphate intake of phosphorus binders caused 35% decrease in plasma FGF23 level." (PMID 26321027, 2015).
short bowel syndrome (1 paper, 2017). "In the present case, our patient's FGF23 level was quite high (314 pg/mL) and was accompanied by low levels of 1,25(OH)2D, PTH, and tubular maximum reabsorption of phosphate per glomerular filtration rate in addition to malabsorption of phosphate due to short-bowel syndrome." (PMID 28953654, 2017).
spindle cell neoplasm (1 paper, 2012). A benign or malignant neoplasm characterized by the presence of neoplastic spindle cells. "Confirmation of PMTMCT was obtained by CT guided needle biopsy which revealed a low grade spindle cell neoplasm with positive FGF-23 mRNA expression by RT-PCR." (PMID 23346426, 2012).
squamous cell carcinoma (1 paper, 2023). A carcinoma arising from squamous epithelial cells.
steatosis (1 paper, 2024). Increased lipid within the cytoplasm of cells. "Although ETs do not regulate cell steatosis but cause inflammation in HepaRG and HCC cells, here, we further investigated the effect of ETs (single exposure and in combination) on the expression of cell fibrosis markers such as AST, FGF-23, Cyt-7, p21, TGF-β, TIMP2, and MMP2." (PMID 39771071, 2024).
systolic heart failure (1 paper, 2018). Heart failure caused by abnormal myocardial contraction during systole leading to defective cardiac emptying. "Such impaired contractility effect may at least in part support clinical findings of high FGF23 levels in patients with systolic heart failure and of FGF23-associated LV dysfunction in the absence of LVH." (PMID 30200452, 2018).